RNU6-604P (RNA, U6 small nuclear 604, pseudogene)
Gene: Small nuclear RNA gene on chromosome 7 (151,900,275 to 151,900,374, forward strand). Ensembl gene ENSG00000212219.
Homologues: Orthologues: chimpanzee U6 (99% identical), macaque U6 (97% identical), dog U6 (69% identical), guinea pig U6 (66% identical), dog U6 (61% identical). Paralogues in human: RNU6-1005P (74% identical), RNU6-627P (74% identical), RNU6-838P (74% identical), RNU6-1241P (73% identical), RNU6-1249P (73% identical), RNU6-12P (73% identical), RNU6-1340P (73% identical), RNU6-13P (73% identical), RNU6-32P (73% identical), RNU6-61P (73% identical), RNU6-737P (73% identical), RNU6-787P (73% identical), and 1285 more.